FGFR1 (fibroblast growth factor receptor 1)
Diseases named in the same sentence as FGFR1 in open-access papers (continued):
Sharing a sentence is not in itself a finding about the gene and the disease.
tumor (continued). "Previous studies have shown that activation of inducible FGFR1 (iFGFR1) in mammary epithelial cells resulted in increased proliferation, migration, and invasion in vitro and tumor formation in vivo." (PMID 23029290, 2012). "Brivanib, a dual VEGFR-2/FGFR-1 kinase inhibitor, reduced tumor proliferation, vascular density, and microcirculation; inhibited VEGF- and FGF-driven angiogenesis; and induced apoptosis in tumor xenograft models." (PMID 23057939, 2012). "As FGFR3 and FGFR1 are altered in the majority of superficial tumours and in a good proportion of invasive tumours, they represent very inviting therapeutic targets." (PMID 22899908, 2012). "The six cases showing FGFR-1 gains in the primary tumour again showed FGFR-1 gains in the metastases." (PMID 23270564, 2012). "Whereas all the mice injected with the three different tumors in the control groups had died by day 50 after tumor cell injection, 80% of the mice in the FGFR-1-vaccinated group were still alive." (PMID 21385454, 2011). "When the FGFR-1 vaccine was administered 7 days after inoculation of tumor cells, the mice had prolonged survival with significantly reduced tumor size compared to controls." (PMID 21385454, 2011). "To determine the cellular requirement for genes in the region targeted by the amplification, we assessed the requirement of WHSC1L1, LETM2 and FGFR1 expression for tumor maintenance by depleting them individually using shRNA." (PMID 21666749, 2011). "Both bFGF and FGFR-1 have been targeted by vaccines to reduce tumor size in pre-clinical mouse models." (PMID 21385454, 2011). "From network 2, we validated FGFR1 (with the highest fold of upregulation in this network) to be important in CR disease in vitro and in clinical tumours." (PMID 21952621, 2011). "It is highly likely that A2C9-1 suppresses tumor cell growth through a similar mechanism by targeting IFN-induced FGFR1." (PMID 21573021, 2011). "Kaplan–Meier graphs of tumours were plotted to analyse if enhanced FGFR1 expression in CRPC, when compared with matched HNPC, was related to patient survival outcome." (PMID 21952621, 2011). "Specifically, three primary tumor samples with amplified FGFR1 and LETM2 genes had amplicon breakpoints within WHSC1L1, explaining the exclusion of WHSC1L1 from the GISTIC amplification peak." (PMID 21666749, 2011). "Intramuscular vaccination of the Xenopus FGFR-1 plasmid before injecting tumor cells subcutaneously (Meth A fibrosarcoma, H22 hepatoma, or MA782/5 S breast cancer) led to an 80% or greater reduction in tumor size compared to the control." (PMID 21385454, 2011). "Among the four different types of FGFRs, FGFR1 and FGFR2 have been specifically linked to tumour cells, and bFGF binds to FGFR1." (PMID 20606682, 2010). "Immunohistochemical analysis of SPARC protein expression of tumours over-expressing FGFR1-IIIb revealed that SPARC protein was up-regulated in FGFR1-IIIb over-expressing tumours." (PMID 19920824, 2010). "In contrast, in tumours with strong FGFR1 expression as well as strong Sef expression, only 24% had evidence of bone metastasis (P<0.001)." (PMID 19888221, 2009). "Here we investigate the sub-cellular distribution of syndecan-1, FGF-2, FGFR-1 and heparanase in malignant mesenchymal tumor cells, and explore the possibility of their coordinated translocation to the nucleus." (PMID 19802384, 2009). "Levels of expression varied among tissues, with the ASV derived from VEGFR1, Met, and FGFR1 being predominantly expressed in tumor tissues." (PMID 18593464, 2008). "FGFR1 amplification was observed in 8.7% of the tumours and was significantly more prevalent in patients >50 years of age and in tumours that lacked HER2 expression." (PMID 17397528, 2007). "FGFR-1 is expressed in early hematopoietic/endothelial precursor cells, as well as in a subpool of endothelial cells in tumor vessels." (PMID 17316436, 2007).
tumor (continued). "Subgroup analysis demonstrated that the independent prognostic impact of FGFR1 amplification was only seen in patients with oestrogen-receptor-positive tumours, where FGFR1 amplification was the strongest independent predictor of poor outcome." (PMID 17397528, 2007). "Tumor cells exhibited strong cytoplasmic staining for FGFR1, whereas normal glandular cells were moderately positive, and the majority of stromal cells were weakly positive." (PMID 17244359, 2007). "After excluding the uninformative tissue microarray cores, results on FGFR1 amplification were available for 496 tumours." (PMID 17397528, 2007). "Subgroup analysis revealed that FGFR1 amplification was an independent prognostic factor for disease-free survival and overall survival only in ER-positive tumours." (PMID 17397528, 2007). "In pancreatic ductal adenocarcinoma, enforced expression of FGFR1-IIIb exerts tumor-suppressive effects by inhibiting proliferation, migration, invasion, and xenograft growth, primarily through suppression of ERK1/2 activity alongside activation of p38 and JNK signaling." (PMID 41584352, 2026). "In vivo subcutaneous xenograft models were used to evaluate the role of FGFR1 in tumor growth." (PMID 41946672, 2026). "Blocking HMGA1, FGFBP1, or FGFR1 also reduced stromal formation and increased tumor necrosis." (PMID 41943828, 2026). "Such a fusion event could lead to the overexpression or activation of FGFR1, thereby promoting tumor progression." (PMID 40242904, 2025). "FGFR1 fusions with various partner genes have been identified in several tumor types." (PMID 40547805, 2025). "This suggests that FGFR1-driven MIBC are characterized by HGF-rich tumor microenvironments, which may promote the expansion of MET-amplified subpopulations within heterogeneous tumors during erdafitinib treatment." (PMID 41315241, 2025). "One significant driver is FGFR1 amplification, which enhances tumor growth and complicates therapy." (PMID 39941826, 2025). "Such approach could further enhance antitumor efficacy by targeting FGFR1-overexpressing tumor cells." (PMID 40547805, 2025). "Therefore, using monoclonal antibodies and tyrosine kinase inhibitors to target FGFR1 and enhancing ICIs by modifying the tumor microenvironment and combating immune suppression represents a potential therapeutic strategy." (PMID 41424604, 2025). "Fibroblast Growth Factor Receptors (FGFR), a family of four tyrosine kinase receptors (FGFR1-4), have emerged as potential cancer targets, since FGFR alterations (gene amplifications, mutations, rearrangements/fusions) contribute to tumour development and progression." (PMID 40467542, 2025). "In xenograft models, triple inhibition strongly suppressed tumor regrowth, suggesting that initial blockade of FGFR1 may be pivotal for preventing resistance." (PMID 39941826, 2025). "The binding of infigratinib to FGFR1 has been extensively validated in various tumor models." (PMID 41226200, 2025). "However in AB740 which showed high copy number gain (8 copies) and high protein expression of FGFR1, we observed a significant inhibition of tumor growth in vivo." (PMID 41202566, 2025). "By targeting multiple tyrosine kinase receptors, including FGFR1–4, lenvatinib may suppress the metastatic potential of tumor cells." (PMID 40940915, 2025). "In all these cancers, FGFR1 plays a significant role in driving tumor development and progression." (PMID 40547805, 2025). "We observed higher levels of FGFR1 expression following miR-181b delivery in malignant tumor cells." (PMID 40149537, 2025). "Furthermore, activation of FGFR1 triggers the expression of the chemokine CX3CL1 in the tumour microenvironment through NF-κB signalling." (PMID 40135140, 2024). "Tumor recurrence was more frequent in FGFR1-mutant tumors than in BRAF V600E-mutant tumors." (PMID 39081340, 2024). "Additionally, small molecule inhibition of BET proteins and FGFR1 simultaneously induces synergy in reducing GBM tumor growth in vitro and in vivo." (PMID 38654040, 2024).
tumor (continued). "In addition, one tumor each had a NTRK3 fusion (ETV6-NTRK3), a PTEN deletion, an FGFR1 GOF mutation (K654E), a CHEK2 LOF mutation (T367fs*), and an Aurora kinase A fusion (AURKA-CSTF1)." (PMID 38730662, 2024). "This suggests that FGFR1 overexpression in different tumour types may be due to specific hypomethylated promoter sites." (PMID 40135140, 2024). "Considering the significant involvement of both Tie2 and FGFR1 in tumor angiogenesis, it is plausible to assume that the synergistic inhibition of these two pathways may contribute to the remarkable antiangiogenic efficacy of brassinin." (PMID 38792249, 2024). "The FORT-2 trial is a phase 1b/2 trial of rogaratinib, an oral pan-FGFR1-4 inhibitor, plus atezolizumab compared to placebo plus atezolizumab in patients with untreated cisplatin-ineligible mUC that have a tumor with high (3+ or 4+) FGFR1 or FGFR3 mRNA expression by RNAscope." (PMID 38254823, 2024). "Increased FGF9 release in CAFs activates FGFR1 signaling in tumor cells with Klf5KR knockin." (PMID 38781024, 2024). "However, studies have indicated that the inhibitory effects of TKIs on FGFR1 vary among different tumor types." (PMID 39590377, 2024). "Specifically, the use of the eIF4A inhibitor Zotatifin in TNBC mouse models suppressed the translation of Sox4 and Fgfr1, resulting not only in the inhibition of cell proliferation but also in increased interferon response and remodeling of the tumor immune microenvironment." (PMID 38473804, 2024). "In various human malignancies, FGFR1 gene translocation, mutation, and amplification can result in the abnormal activation of the FGFR signaling system, thereby promoting carcinogenesis and tumor progression." (PMID 39391879, 2024). "FGFR1 amplification has been reported in a subset of human SCLC tumor samples (6–30%)." (PMID 38892831, 2024). "In summary, FGFR1 is a key regulator of tumor growth and invasion." (PMID 38255923, 2024). "Here, we report that PTEN deficiency induced Krüppel-like factor 5 (KLF5) acetylation and that interruption of KLF5 acetylation orchestrated intricate interactions between cancer cells and CAFs that enhance FGF receptor 1 (FGFR1) signaling and promote tumor growth." (PMID 38781024, 2024). "It has been shown to significantly inhibit tumor growth in FGFR1-dependent human xenograft models without causing weight loss in tumor-bearing mice." (PMID 39590377, 2024). "Despite their potential anti-tumor activity, they are ineffective at overcoming commonly acquired FGFR gatekeeper mutations (FGFR1 V561M, FGFR2 V564F, FGFR3 V555M, FGFR4 V550M/L) and other mutations including an FGFR1 N546K mutation and FGFR2 N550H mutations." (PMID 38255923, 2024). "Additionally, the tumor (estimated at 100% tumor content) was found to harbor an in-frame deletion in PIK3R1 p.Ile442_Thr454del and a recurrent hotspot missense variant in FGFR1 p.Lys656Glu." (PMID 39309743, 2024). "HRD tumors are enriched with immunogenic epithelial cells, FGFR1+PDGFRβ+ myCAFs, M1 macrophages, tumor reactive CD8+/CD4+ Tregs, whereas HRP tumors are enriched with HDAC1‐expressing epithelial cells, indolent CAFs, M2 macrophages, and bystander CD4+/CD8+ T cells." (PMID 39136172, 2024). "We showed significant anti-tumor effects of FGFR1–3 inhibition with AZD4547 in EOC models." (PMID 38273381, 2024). "We reasoned if FGFR1 CN is amplified in metastatic lesions, it could potentially be amplified starting at the earliest stages of metastasis, invasion out of the primary tumor." (PMID 38827528, 2024). "FGFR1 is a promising therapeutic target and prognostic marker in different tumor types." (PMID 37445817, 2023).
tumor (continued). "FGFR1–4 genes are often subjected to amplifications that are detected across multiple tumor types, and such events may lead to the overexpression of the respective genes." (PMID 37891989, 2023). "For example, in Case #39, the clonal prevalence of the subclone labelled G, containing mutations in FGFR1, KMT2D, MYC driver genes, was ~0.27 in the pre-treatment tumour biopsy, decreased to ~0.22 in post cycle 1 treatment tumour biopsy but increased to ~0.34 in the lymph node biopsy." (PMID 37758711, 2023). "FGFR1 and FGFR3 expression was determined via IHC on the primary patient tumour, PDXs and PDXOs and very low expression of FGFR1 and FGFR3 were noted in those with high FGFR2c expression confirming that the FGF2/FGFR2c autocrine loop is the target of BGJ398 in these models." (PMID 38062117, 2023). "Given the lack of amino acid homology between GREM1 and FGF1/2 ligands, it will be interesting to explore whether GREM1-mediated FGFR1 signaling contributes to normal biological processes and/or other human tumor phenotypes." (PMID 37615860, 2023). "Of note, a previous study demonstrated that isoform switching of FGFR1 promotes tumor invasion." (PMID 37579831, 2023). "Moreover, FGFR1 has been correlated with tumor development and lung metastasis in xenographic models, whereas its activation improved survival and radiation resistance, a phenotype which was reversed when FGFR1 was inhibited." (PMID 36839989, 2023). "FGFR1 might promote PCa progression through activation of oncogenic pathways and increase of resistance to anti-tumor drugs." (PMID 37993879, 2023). "Likewise, ablation of FGFR1 resulted in a profound reduction in tumor invasion in xenografted GBM tumors." (PMID 37579831, 2023). "No variation in term of OS, age at diagnosis and tumour location was noted according to FGFR1-mutated variant: FGFR1N546K/D versus FGFR1N656E (online resource)." (PMID 38066305, 2023). "This pattern of tumor may be explained by the role of FGFR1 in neural development, in particular of the diencephalon area." (PMID 37524847, 2023). "LMP1 is an oncogene that regulates multiple cellular processes for tumor transformation, including activation of fibroblast growth factor receptor 1 (FGFR1) 50, increased aerobic glycolysis through mTORC1 51, and promotion of epithelial-mesenchymal transition (EMT) 52-54." (PMID 36632221, 2023). "The negative regulator of FGFR1, namely, circFGFR1‐encoded circFGFR1p, inhibits tumor cell development due to the absence of the tyrosine kinase structural domain." (PMID 37750089, 2023). "Taken together, the results of in vivo efficacy studies on cell-line xenograft tumor models with different FGFR aberrations show that CPL304110 exhibits a potent broad spectrum of antitumor activity against FGFR1, 2, and 3, which represent different types of tumor histology in the clinical setting." (PMID 38282676, 2023). "In particular, the detected rearrangements in PDX003 and PDX008 showed strong similarities to those found in the FGFR inhibitor–responsive tumor from patient TUM009 and the cancer cell line H1581, indicating recurrent rearrangements associated with FGFR1 dependency." (PMID 37606995, 2023). "It is also important to note that in a recent study, miR-34a and miR-34b/c gene silencing decreased apoptosis and cell viability and increased tumor grade as well as inducing the expression of lymph node metastasis-associated genes, including INHBB, AXL, FGFR1, and PDFGRB." (PMID 38116556, 2023). "In tumor tissues, a weak positive correlation was found between FGFR1 gene and protein expression (Spearman rho 0.257), and the relative FGFR1 expression was overall higher in FGFR1-high tumors compared with FGFR1-low tumors (P<0.001)." (PMID 37546410, 2023). "In addition, multi-targeted RTK inhibitor Pazopanib also exhibited superior sensitivity in the high RS tumor, owing to its FGFR1 inhibition activity." (PMID 36105076, 2022).
tumor (continued). "Accordingly, FGFR1 is considered as a promising target for the treatment of tumor angiogenesis." (PMID 35884601, 2022). "Tumor cell–derived FGFBP1 induces FAPα expression in HSCs via the FGF2/FGFR1/ERK1/-2/EGR1 axis." (PMID 35951441, 2022). "Among the seven tumours without available methylation profiling, FGFR1 status was obtained for six (two ITDs, one mutation and three wild type)." (PMID 35836307, 2022). "Because in two cases a FGFR1 alteration in combination with PIK3CA or PIK3R1 mutation was present, the authors questioned whether such samples may represent a yet-to-be defined tumor class of RGNT outside of the stereotypic location in the fourth ventricle." (PMID 35018490, 2022). "Furthermore, in this study, overexpression of miR-214-3p was found to exhibit synergistic effects with the FGFR-1 inhibitor AZD4547 in terms of decreasing tumor growth in both in vitro and in vivo models." (PMID 36471277, 2022). "Hence, patients showing a poor tumor response (Miller–Payne grades 1–3) had significantly more FGFR1 gene amplification (p = 0.024)." (PMID 35213975, 2022). "However, as FGFR1 is also expressed on tumor cells, we here cannot exclude the contribution of the activation of FGFBP1/FGF2/FGFR1 signaling in tumor cells for vessel co-option." (PMID 35951441, 2022). "Additionally, FGFR1 amplification together with mRNA and protein overexpression were observed in this tumor." (PMID 36142417, 2022). "Both the FGF2-neutralizing antibody and PD-166866 inhibited the expression levels of p-FGFR1 and FAPα in HSCs, suppressed the recruitment of Gr-1+ MDSCs, decreased the expression of vimentin, and increased the expression of E-cadherin in tumor cells." (PMID 35951441, 2022). "FGFR1 mutations were associated with oligodendroglia-like cells, but not with age or tumor location." (PMID 35018490, 2022). "Since we found that FGFR1 was significantly positively correlated with many immune cells and had a high correlation coefficient, we wondered whether overexpression of FGFR1 could form a hot tumor, thereby improving the immunotherapy effect." (PMID 36147913, 2022). "FGFR1 expression has recently been linked to the highly negative correlation between FGFR1 mRNA and methylation levels (average of three CpG sites: cg10823844, cg15791248, and cg27646230) in tumor samples." (PMID 36142417, 2022). "Interestingly, concomitant inhibition of FGFR1 and EGFR showed synergistic action on tumor regression in EGFR-mutated, FGFR1-overexpressing xenograft models." (PMID 36482474, 2022). "Given the pivotal roles of both Tie2 and FGFR1 in tumor angiogenesis, we assume that the combined blockade of these two pathways may be the reason for the high anti-angiogenic efficiency of brassinin." (PMID 35884601, 2022). "Moreover, the role of FGFR1 in other cancers has potential to open EGFR therapy in the other tumor types." (PMID 36054194, 2022). "FGFRs might be anti-tumor therapeutic targets, as FGFR-1 amplification occurs in approximately 20% of patients with SqCLC and is associated with a poor prognosis." (PMID 36703957, 2022). "FGFR1 inhibition impacts on cancer cell growth by affecting glucose energy metabolism, and could be an important therapeutic option across multiple tumor types." (PMID 36185201, 2022). "Transcription factors like NOTCH1 (16%) and KMT2B (16%), UNC13C (14%), another tumor suppressor, ERCC2 (14%) involved in nucleotide excision repair pathway, were recurrently mutated, whereas genes like CDKN2A, MLH1, FGFR1, EGFR, etc. had a less than 10% mutation frequency." (PMID 34796107, 2021). "The increase of FGFR1 expression in spindloid tumours was confirmed at the protein level." (PMID 33772015, 2021).